DMD (dystrophin)
Diseases named in the same sentence as DMD in open-access papers (continued):
Sharing a sentence is not in itself a finding about the gene and the disease.
tumor (continued). "Additional RNAseq and qRT-PCR analyses of oropharyngeal squamous cell carcinoma (OPSCC) tissues revealed DMD as one of a number of large CFS genes to be significantly downregulated in tumour tissues." (PMID 33188621, 2021). "For some carcinomas, the DMD gene and/or its protein products appear to be tumour suppressive, whereas in others they appear to be oncogenic." (PMID 33188621, 2021). "Of the 55 patients with progressive/high grade tumours evaluated, 17 (32%) either exhibited deletions in the DMD gene or silenced expression." (PMID 33188621, 2021). "Recent data have emerged suggesting that dystrophin can act as a tumor suppressor and limits metastasis in myogenic cancers." (PMID 34301934, 2021). "DMD deletions are then detected because the locus fits these features and deletions have a tumor suppressor impact on oncogenesis." (PMID 32438562, 2020). "Array CGH analysis of hybrid tumors specifically evidenced focal recurrent intragenic deletions targeting DMD in 82% of cases, and occurring only after in vivo tumor growth." (PMID 32438562, 2020). "Deletion of dystrophin (DMD), a tumor suppressor gene in human cancers with a myogenic program, has been reported as a late genetic event associated with the development of metastatic potential in GIST." (PMID 30867899, 2019). "Dystrophin has been shown to behave as a tumor suppressor, and in a large series of GISTs genomic mechanisms of dystrophin inactivation were present in 96% of metastatic GIST, but absent in low-risk GIST." (PMID 30867899, 2019). "The high rate of DMD deletions found in ONBs coupled with the emerging tumor suppressor activity of dystrophin suggests a central role for DMD in the pathogenesis of this tumor type." (PMID 30575736, 2018). "In this study, the deletion of DMD occurred mainly in tumors with a high mitotic index of the primary tumor and in metastatic lesions." (PMID 29510530, 2018). "The study and validation of DMD as a new player in tumor development and as a new prognostic factor for tumor progression and survival are warranted." (PMID 27391342, 2017). "The evidence of dystrophin tumor suppressor suggests that other components in dystrophin complex are likely to play key roles in GIST tumorgenesis." (PMID 28947997, 2017). "The analysis of RNAseq studies revealed a median frequency of DMD genetic alterations of 3.4%, higher or similar to other well-known tumor suppressor genes." (PMID 27391342, 2017). "The mechanisms regulating DMD intron 40 retention should be further clarified in other tumor-derived cells." (PMID 28546788, 2017). "Other studies demonstrated that DMD Dp71 plays a central role in proliferation, invasion and migration in vitro and suppressed tumor growth in xenograft models." (PMID 27391342, 2017). "In concordance to the previous reports suggesting the tumor suppressor role of DMD, we found that DMD expression was decreased in the majority of the analyzed tumors compared to the normal tissues." (PMID 27391342, 2017). "Three activated UPRs associated with immune activation were unique to CPA/6d-treated GL261(B6) tumors: EIF2AK2, IFNL1 and MAVS, while the two activated UPRs specific to GL261(scid) tumor responses, DMD and SPARC, have glial cell-related functions:." (PMID 27515027, 2016). "Recently, dystrophin has also been proposed as a tumor suppressor through the regulation of invasion and migration in myogenic cancers." (PMID 26568816, 2015). "CDKN2A, PIK3CA, RASA1 and DMD variants were exclusively linked to smoking, chewing, HPV infection and tumor stage." (PMID 26834999, 2015). "Mice with mutations in the Dystrophin (DMD), Calpain-3 (LGMD2A) or Dysferlin (LGMD2B) genes are susceptible to malignant tumours originating from the skeletal muscles 1–4 (reviewed in 5)." (PMID 24341522, 2014).
tumor (continued). "When starting to study age-related phenotypes of murine MDs, we have observed the frequent and spontaneous occurrence of skeletal muscle-derived tumors in our colony of C57BL/10-mdx mice, suggesting a tumor-suppressive role of dystrophin in mice." (PMID 21533183, 2011). "The distinct pathway enrichment profiles and our survival and alteration frequency analyses presented above support a context‐dependent role for DMD (and most notably, the Dp71ab gene product) in cancer, which reconciles conflicting reports of its oncogenic versus tumour‐suppressive functions." (PMID 40832923, 2026). "This suggests that the effect of DMD expression on survival across several tumour types may be attributed to Dp71ab expression." (PMID 40832923, 2026). "This highlights a complex relationship between DMD expression and tumour aggressiveness." (PMID 40832923, 2026). "Investigating the mechanistic roles of DMD gene product expression in driving tumour aggression and/or modulating oncogenic transcriptional programs was beyond the scope of this in silico study; this remains a critical knowledge gap that warrants a focused in‐depth investigation." (PMID 40832923, 2026). "While this balance may still play a role, our updated model expands on this by demonstrating that total DMD expression, in a context‐dependent manner, is also a critical determinant of tumour behaviour." (PMID 40832923, 2026). "Notably, a significant correlation between dystrophin protein expression and patient survival is observed, reinforcing survival trends seen at the RNA level and demonstrating the clinical relevance of dystrophin protein localisation in tumour biology." (PMID 40832923, 2026). "Thus, individuals with high DMD expression within HNSCC tumours survive longer than patients with low DMD expression." (PMID 40155657, 2025). "Interestingly, this contrasts with other tumour types such as low-grade glioma (LGG) where our in-depth bioinformatic analysis revealed a detrimental effect of high DMD expression on survival." (PMID 40155657, 2025). "Full length TAp63 isoforms have tumour-suppressor functions while N-terminally truncated ΔNp63 isoforms have oncogenic properties, this is strikingly similar to what we observe with different dystrophin protein products." (PMID 40155657, 2025). "Therefore, to further develop our understanding of the role of the DMD gene in cancer, and to highlight tissue-dependent effects, here we used HNSCC to exemplify tumours where high DMD expression appears protective." (PMID 40155657, 2025). "Tumor‐associated muscle wasting is exacerbated in mice lacking dystrophin, but restoration of dystrophin expression can attenuate this muscle wasting." (PMID 39001580, 2024). "As for NCR mutations, 98.2% of tumor samples (6632 out 6751) had no mutations in the non-coding regions of the DMD gene." (PMID 36900171, 2023). "The majority of tumor cell lines had no identified mutations within the DMD gene region (n = 773), while the remaining had missense (n = 120), truncating (n = 11), splice (n = 4), and multiple mutations (n = 13)." (PMID 36900171, 2023). "Alternative splicing is a discernible feature of DMD transcripts found in the analyzed samples, with the splice variant Dp71b lacking exon 78 having the highest mean abundance level of all DMD transcripts across the analyzed tumor and control tissues, followed by Dp427m." (PMID 36900171, 2023). "Next, we investigated whether the transcriptomic changes resulting from DMD downregulation in primary tumors and tumor cell lines are similar to those observed in skeletal muscles of DMD patients." (PMID 36900171, 2023). "The majority of tumor samples had no identified CR mutations in the DMD gene locus (6201 out of 6751)." (PMID 36900171, 2023).
tumor (continued). "We confirmed dystrophin protein is variably expressed in LGG tumour tissue by immunohistochemistry and, overall, demonstrate that DMD expression has potential utility as an independent prognostic marker which can further stratify IDH mutant LGG to identify those at risk of poor survival." (PMID 35217778, 2022). "Whilst we have confirmed dystrophin protein is expressed in LGG tumour tissue, further work is needed to experimentally confirm our findings in for e.g. a large immunohistochemical cohort as well as to investigate the potential involvement of DMD gene product(s) in LGG tumourigenesis." (PMID 35217778, 2022). "Recently, findings in tumor bearing mice have uncovered a new feature of cachectic muscles, which includes plasma membrane irregularities associated with loss of the principle component of the dystrophin glycoprotein complex (DGC), dystrophin." (PMID 33467597, 2021). "As with other tumour types, it remains to be seen whether DMD plays a key role in the pathogenesis of B-CLL or whether its altered expression represents a secondary event." (PMID 33188621, 2021). "In this cell line, three retained introns (40, 58 and 70) accumulating in 90% of DMD transcripts are present, which are thought to abolish dystrophin expression through the introduction of stop codons and, thereby, disruption of the tumour suppressive role of Dp427." (PMID 33188621, 2021). "In this group, a heterozygous deletion (H4-LP-Tumor3) and/or a heterogeneous representation of DMD deletion in the tumor could be an explanation for the weak expression of Dp427." (PMID 32438562, 2020). "Somatic DMD aberrations were noted in 50% of tumor samples that underwent WGS." (PMID 31341965, 2019). "In addition, a recent study based on genomic data from public repositories of diverse cancer types, showed that DMD expression was decreased in the majority of the analysed tumours." (PMID 29596374, 2018). "In addition, a focal deletion of dystrophin gene (DMD) on chromosome X was found in 42% of tumor samples (corresponding to four patients: P03, P06, P07, and P08)." (PMID 29510530, 2018). "The involvement of the DMD gene in tumorigenesis has indicated that dystrophin may act as a tumor suppressor." (PMID 28546788, 2017). "Interestingly, it has been recently reported that DMD is involved in the development and progression of myogenic tumors, assigning DMD a tumor suppressor activity in these types of cancer." (PMID 27391342, 2017). "Interestingly, it has been reported that DMD and its partners (e.g. dystroglycan, dysferlin, calpain-3, Large) are involved in tumor development and progression." (PMID 27391342, 2017). "Dystrophin, a cytoskeletal protein, has been reported to be reduced in tumor-bearing mice." (PMID 24400146, 2013). "The spontaneous occurrence of skeletal muscle-associated tumors in different dystrophin-deficient mouse lines independent of the underlying dystrophin gene mutation supported a candidate tumor suppressor role of dystrophin." (PMID 21533183, 2011). "In order to test if dystrophin, dysferlin and calpain-3 have tumor-suppressor effects in vivo, we generated double-mutant mouse lines, i.e. dystrophin-deficient (mdx) mice with additional lack of either dysferlin (Dmd −/− Dysf −/−) or calpain-3 (Dmd −/− Capn3 −/−)." (PMID 21533183, 2011). "Following engraftment into immunodeficient dystrophin-deficient mice, H2K 2B4 cells regenerated host muscle with donor derived myofibres that persisted for at least 24 weeks, without forming tumours." (PMID 21935475, 2011). "We therefore hypothesised that tumours in the DMD‐suppressor group (where high DMD is beneficial) may possess a higher intrinsic potential for invasion and metastasis, which is counteracted by high DMD expression, while those in the DMD‐oncogenic group may be less aggressive and/or invasive." (PMID 40832923, 2026).
tumor (continued). "Whilst we are not implying there is a correlation of DMD with p63 status, our work provides robust evidence for a similar context‐dependent role for DMD, where its high expression may support tumour‐promoting processes in some cancers while reinforcing tumour‐suppressive mechanisms in others." (PMID 40832923, 2026). "This association between DMD expression and age was unique to tumor tissues, as no such association was found by us in the corresponding healthy tissues from the GTEx database, and also in a meta-analysis that identified genes with age-associated expression in human peripheral blood samples." (PMID 36900171, 2023). "IDH mutant LGG patients with high DMD expression in their tumours survive approximately 6 years less than those with low expression; this appears to be particularly relevant for non-1p/19q co-deleted patients since high DMD expression was exceptionally rare amongst 1p/19q co-deleted cases." (PMID 35217778, 2022). "The signal of dystrophin can inhibit the activity of T cells via cytoplasmic nutrient sensors dependent signaling pathway, it also can destroy the intestinal villus and alter nutrient–sensing pathways, and thus decreases the immune function and the body's anti-tumor ability." (PMID 36386538, 2022). "Parallel studies of human RMS have indicated that dystrophin may have roles as a tumor suppressor." (PMID 31054580, 2019). "IR contributes to tumor progression by generating truncated oncogenic proteins, suppressing tumor suppressor genes like TIMP1 and DMD, and enabling cancer cells to adapt to stressors like hypoxia." (PMID 40870034, 2025). "Among them, we selected seven genes associated to cell proliferation and apoptosis that resulted downregulated in tumor samples: BTG1, CCNG1, DMD, EDG1, SEMA3G, SYNPO2, TIMP2." (PMID 39984959, 2025). "Although, as expected, the presence of some types of somatic mutations and SCNAs was associated with lower levels of DMD expression, in about 88% of tumor samples and 77% of cell lines, DMD downregulation could not be linked to mutations in the coding regions of the DMD gene." (PMID 36900171, 2023). "In addition, the overexpression of collagen tissue found in the extracellular matrix of the gastrocnemius muscle could be related to the reduced expression of dystrophin, which has been reported to be a type II fiber-specific condition in tumor-bearing animals." (PMID 37830689, 2023). "Knockdown of Dp71 in DMD-deleted RMS cells inhibited cell growth, suggesting that Dp71 expression is a requirement for myogenic tumours." (PMID 33188621, 2021). "Dystrophin has been shown to act as a tumor suppressor, making intron retention in the DMD a likely mechanism of tumor suppressor inactivation." (PMID 28546788, 2017). "In aggressive cancers, high DMD expression appears to preserve DAPC‐mediated signalling and adhesion, countering metastatic potential, whereas in less aggressive tumours, elevated DMD may drive oncogenic pathways through enhanced cellular remodelling." (PMID 40832923, 2026). "Moreover, in a recent focused study of DMD in HNSCC, we also revealed an upregulation of ECM structure and ECM organisation processes in DMD high versus low tumours, in alignment with the DMD suppressive group presented here." (PMID 40832923, 2026). "The results show that Dp71ab (an isoform lacking DMD exons 71 and 78) is a predominant transcript across all but one tumour type (LAML)." (PMID 40832923, 2026). "Interestingly, only three tumours (THYM, LAML and KIRP) appear to lack full‐length dystrophin transcript expression: Dp427c (cortical promoter), Dp427m (muscle promoter) or Dp427l (lymphocyte promoter)." (PMID 40832923, 2026). "Injection of MG132 reduced muscle loss in cachectic tumor-bearing mice, in immobilized mice, and in zebrafish lacking the DGC component, dystrophin." (PMID 33467597, 2021).
tumor (continued). "The RNAseq data showed that the median frequency of DMD alterations in non-myogenic tumours (3.4%) was higher than that in other common tumour suppressor genes, such as BRCA1 (1.6%), BRCA2 (2.8%) and PTEN (3%)." (PMID 33188621, 2021). "Accordingly, in the tumor H4-LP-Tumor1 (no DMD deletion), Dp427 (green) was detected by immunofluorescence on the FFPE tumor at the membrane of the cells as well as all the other isoforms (red)." (PMID 32438562, 2020). "Subcutaneous injection of DYS‐HAC2‐corrected DMD myoblasts into immunodeficient scid/beige mice (N = 5 per clone) did not result in tumour formation (N = 10; Table EV1)." (PMID 29242210, 2018). "In the tumor from an additional male patient (ENB7PT2), the deletion was 102 kb upstream to the DMD gene but encompassed three CTCF-binding motifs that could affect transcriptional activity." (PMID 30575736, 2018). "DMD may thus connect to the long bristles module and act upstream of Akt-TSC2 signalling in tumor and synapse biology." (PMID 24204314, 2013). "IMR90 cells, on the other hand, seemed to be impacted by a different panel of genes, BTG2, FBXW7, NDUFAF2, PHLDA1, and DMD, whose knockdown did not have a significant impact in the two tumor cell lines, suggesting cell line-specific effects." (PMID 24009623, 2013). "Our findings indicate that DMD does not act uniformly as an oncogene or tumour suppressor." (PMID 40832923, 2026). "Survival trends (and DMD transcript expression) may also not be uniform across all tumour subtypes and may be confounded by clinicopathological variables." (PMID 40832923, 2026). "Dystrophin in tumor cell lines did not correlate strongly with the presence of its established DAPC partners, suggesting that it may have a different role(s) than those in muscle cells." (PMID 36900171, 2023). "None of these observations suggest that DMD acts as a tumor suppressor." (PMID 31266185, 2019). "In addition, unlike DMD and LAMA2 which were deleted, only missense mutations were seen in TTN, as has been reported in a number of other tumor types and is not unexpected given the large size of the TTN gene." (PMID 30575736, 2018). "To ensure that DMD altered expression is not a random event, we evaluated the percentage of the total number of genes that do not change their expression between normal and tumor samples." (PMID 27391342, 2017). "In order to learn whether other MD-genes, which are not directly related to dystrophin, might also suppress tumor formation, we studied mice lacking dysferlin (DysfSJL mutation; Dysf −/−), calpain-3 (Capn3 −/−; knockout), or Large (Largemyd mutation; Large −/−)." (PMID 21533183, 2011). "For example, the high-level retention of introns 40, 58, and 70 in DMD transcripts may be responsible for the lack of dystrophin expression in CRL-2061 cells, resulting in the elimination of the tumor suppressor activity of dystrophin." (PMID 32733531, 2020). "Retention of these introns may have been responsible for the lack of dystrophin expression by CRL-2061 cells, thereby abolishing the tumor suppressor activity of dystrophin." (PMID 28546788, 2017).